CXCL1 (C-X-C motif chemokine ligand 1)
Diseases named in the same sentence as CXCL1 in open-access papers (continued):
Sharing a sentence is not in itself a finding about the gene and the disease.
Obesity (continued). "To test whether the mouse model is appropriate to study the CXCL1 gradient in obesity/cancer, we analysed the systemic circulation of 50 mouse cytokines and chemokines represented in the Luminex panel." (PMID 27241286, 2016). "However, the role of CXCL1 in obesity-related diseases in humans is poorly understood." (PMID 35806156, 2022). "So, the CXCL1/8-CXCR2 axis may appear as a molecular link between obesity and OC." (PMID 34638514, 2021). "In addition, it is reported that CXCL1 gene expression in the liver is elevated, and that the number of myeloperoxidase-positive neutrophils is increased, by provoking Fas-induced apoptosis in the livers of mice with obesity induced by a high-fat diet." (PMID 23875831, 2013). "Other chemokines include but not limited to CCL2 (MCP-1), CCL3 (MIP-1α), CCL4 (MIP-1β), CCL19, CXCL1, CXCL8 or IL-8, CXCL10, and CXCL12 also play an important role in obesity and cancer immunotherapy." (PMID 40863244, 2025). "Strikingly, ob-dT bASCs already displayed an enhanced gene expression of CXCL2, CXCL1, CXCL3, FGF2 and CCL2, compared to ln-dT bASCs, suggesting a crucial impact of obesity on bASCs." (PMID 36710348, 2023). "The receptor ligands in mice are CXCL1 (KC) and CXCL2 (MIP-2), known to regulate neutrophil chemotaxis, and their levels are also elevated in obesity." (PMID 33673387, 2021). "Taken together, these results demonstrate that CXCL1/2 acts downstream of CREB/CRTC and NFκB pathways to promote insulin resistance in obesity." (PMID 34686752, 2021). "Recent data have shown that, along with CXCL5, circulating levels of CXCL1, with high affinity to CXCR2, are markedly increased in the db/db mice and correlate with obesity development." (PMID 34571976, 2021). "Mouse CXCL1 and CXCL2 (CXCL1/2) are well-established functional homologs of human CXCL8 (IL8), whose expression is also induced by NF-κB36–38 in obesity and insulin resistance." (PMID 34686752, 2021). "Adipocytes and OC cells highly express CXCR2, and its ligands CXCL1/8, respectively, indicating that the CXCL1/8-CXCR2 axis is a molecular link between obesity and OC." (PMID 34638514, 2021). "There are several possible mechanisms: First, while adiponectin promotes the differentiation of bone mesenchymal stem cells (BMSCs) in bone marrow to osteoblasts via CXCL1 and CXCL8 up-regulation, subjects with obesity are prone to obtain lower levels of adiponectin." (PMID 40455716, 2025). "Among them, the upregulated gene BCL2A1 is common in CVD, HTN, obesity, and aging; RNF144B and PTGIS are common in HCL, obesity, aging, and CVD; G0S2, CXCL1, ACKR3, and PTPRD are found in HTN, aging, and CVD; TGFB2, CA12, and MSR1 are familiar in obesity, aging, and CVD." (PMID 36035865, 2022). "Additionally, we investigated five genes, PRDM2, CXCL1, PHLDA1, DIDO1, CDA, which were commonly expressed in all datasets including depression, obesity, diabetes, and NASH." (PMID 34833079, 2021). "Although the secretion of the chemokines KC/CXCL1 and MCP-1/CCL2 remained unchanged in 3T3-L1, our results show that leptin's actions on adipocytes contribute to the inflammatory profile characteristic of obesity." (PMID 31920961, 2019). "Nonetheless, neither injection of the major SASP factor Cxcl1 (which increased during obesity) nor inhibition of its receptors had an impact on anxiety-like behavior." (PMID 30612898, 2019). "Because lean mice did not display a CXCL1 dependence of tumour growth, our data suggest that recruitment of ASCs, rather than of MDSCs, accounts for obesity-dependent tumour growth stimulation." (PMID 27241286, 2016). "To assess whether ASCs could be recruited in response to CXCL1 secreted by tumours in obesity, we performed immunofluorescence analysis of CXCR1 and CXCR2, the receptors of CXCL1 and CXCL8." (PMID 27241286, 2016). "Our data indicate that CXCL1 expression in non-malignant prostate epithelium is obesity dependent and is further induced in malignant cells of obese patients." (PMID 27241286, 2016).
Obesity (continued). "High levels of insulin-like growth factor 1 (IGF1) and insulin in obesity downregulate Glycogen synthase kinase 3 beta (GSK3B) activity by phosphorylating its serine residue, thereby altering the IL-17 signaling pathway, including upregulation of CXCL1, CCL20, and IL-6 expression." (PMID 37680632, 2023). "To determine whether reduced ASC recruitment explains the lack of obesity effect on the CXCL1-silenced tumours, we performed flow cytometric analysis of tumour cell suspension." (PMID 27241286, 2016).
Stroke (44 papers, 2011 to 2026). Sudden impairment of blood flow to a part of the brain due to occlusion or rupture of an artery to the brain. "Most upregulated genes acutely after stroke were as expected early-response and inflammation associated genes such as Hspa1a, Cxcl1, Ccl3, and Fos." (PMID 37337154, 2023). "Exploring the association between obesity and cerebral inflammation after stroke, obese mice fed a high-fat (60%) diet showed larger post-stroke infarct volumes and increased chemokine expression (CXCL-1 and CCL3), blood-brain barrier (BBB) permeability, and neutrophil and microglia counts." (PMID 38992073, 2024). "Notably, analysis of 341 DE mRNA associated with stroke (259 upregulated, 82 downregulated) in the IR group revealed upregulation of genes like Ccl2, Cxcl1, C3, Serpine1, Adamts7, Csf3, Ptx3, MMP8, Lif, and Lcn2, and downregulation of Gdf10, Agtr2 and Shank3." (PMID 39170713, 2024). "When injected into the brain, both stroke-derived and inflammation-derived EVs induced pro-inflammatory cytokine gene expression (IL-1β and CXCL1), suggesting a potential role in neuroinflammation." (PMID 41751898, 2026). "Female MMP-3 KO stroke brains also had decreased expression of blood cell adhesion genes Pecam1 and Icam2, and decreased expression of inflammatory response genes Ccr1, Cxcl1, Mmp9, Il4ra, Il6, and Il1rn." (PMID 39000490, 2024). "Concentrations of CXCL1 were significantly elevated in dogs with stroke (mean = 436 pg/ml, median = 466 pg/ml, range = 157–681 pg/ml) compared to control dogs (mean = 267 pg/ml, median = 267 pg/ml, range = 210–352 pg/ml) (p = 0.01)." (PMID 37266378, 2023). "High CXCL1 levels measured in the cerebrospinal fluid of stroke patients have been shown to correlate with larger infarct volumes, supporting the view that CXCL1 plays a critical role in the pathophysiology of stroke." (PMID 33924148, 2021). "Consistent with increased IL-17A levels, we detected a significant upregulation of Cxcl1 and Mmp3 transcripts in the whole brain mRNA and a significant increase in absolute numbers of neutrophils at day 3 post-stroke in Il10−/− mice, respectively." (PMID 34772416, 2021). "Given the age-related increases in neutrophil-activating cytokines in mice after stroke, we next examined serum levels of IL-6 and IL-8 (the human homolog of murine CXCL1) in ischemic stroke patients and controls at 24 hours." (PMID 31927534, 2020). "It is noted that chemokine CXCL1, a neutrophil-activating protein, is substantially increased in stroke and significantly reduced by the BR therapy at an early time point post stroke." (PMID 32843630, 2020). "Taken together with our previously published data, we conclude that let-7g* and miR-98 diminish stroke-induced increase in CXCL1 and IP-10 protein levels, respectively, by direct targeting their 3′ UTR sequence." (PMID 32766248, 2020). "The data demonstrated that BR therapy significantly reduced the levels of proinflammatory cytokines interleukin (IL)-1β, IL-6, TNF-α, and the chemokine, CXCL1, at 8 h post stroke and further reduced IL-6, IFN-γ, and TNF-α at 23 h post stroke." (PMID 32843630, 2020). "In line with the changes of cell numbers in blood of stroke mice, the levels of proinflammatory cytokines and the chemokine, CXCL1, in plasma were also altered." (PMID 32843630, 2020). "Multiple reports have suggested a role for aberrant CXCL1/CXCR2 signaling in adult CNS injury including stroke, traumatic brain injury (TBI), temporal lobe epilepsy, neuropathic nociception, central sensitization, and mechanical hypersensitivity." (PMID 31001130, 2019). "In TBI and stroke, cerebral CXCL1/CXCR2 levels determine the magnitude of neutrophil infiltration, subsequent neuronal loss, and infarct volume." (PMID 31001130, 2019). "CXCL1, also known as growth-related oncogene, was reported to be elevated in the cerebrospinal fluid of stroke patients during the immediate early phases." (PMID 31183363, 2019).
Stroke (continued). "In 2005, Losy observed that there was higher CXCL1 in cerebrospinal fluid level than the control group in stroke patients, and suggested the potential neutrophil chemoattractant function in the pathophysiology of stroke." (PMID 27213359, 2016). "In the present study, enhanced chemokine (CXCL-1) expression was observed in the blood at 4 h after stroke in obese mice that had greater damage." (PMID 26239227, 2015). "In response to stroke, chemokine (CXCL-1) expression in the plasma and liver was significantly different in obese mice (6-month high-fat fed), and a greater number of neutrophils were detected in the liver of control but not obese mice." (PMID 26239227, 2015). "Interestingly, cromolyn treatment led to a significant downregulation of both IL-6 and CXCL1 levels in the blood plasma post-stroke." (PMID 37805585, 2023). "In cases of stroke, the levels of CXCL1 also positively correlate with area of ischemic tissue." (PMID 37765263, 2023). "Similarly, KC (CXCL1, a chemoattractant factor for neutrophils) levels were significantly elevated in the blood plasma 3 days (P < 0.05) after stroke compared to sham controls." (PMID 37805585, 2023). "And synergistic with TNF-α, IL-17a could enhance astrocytes to secrete CXCL1, leading to enhanced neutrophil infiltration in a mouse model of stroke." (PMID 35432162, 2022). "With our protocol, we were indeed able to show in vivo that astrocytes express Cxcl1 after stroke." (PMID 35384588, 2022). "The significant change of CXCL1 at early stroke suggests that neutrophils might have played an important role in stroke and involved in BR therapy." (PMID 32843630, 2020). "In response to stroke, both obese ob/ob and control ob/– mice had significantly increased concentrations of plasma and liver IL-6, and plasma granulocyte-colony stimulating factor (G-CSF) and CXCL1." (PMID 28798136, 2017). "Increases in plasma CXCL1 have also been observed after stroke in diet-induced obese mice." (PMID 28798136, 2017). "Here, we found an increased plasma response in IL-6, CXCL1 and G-CSF in obese mice after stroke." (PMID 28798136, 2017). "An increase in the hepatic expression of CXCL-1 has also been reported after experimental stroke." (PMID 26239227, 2015). "However, one third of the genes were increased with suboptimal timing in aged rats, either on day 3 post-stroke (Adam17, Gpc3, Mmp14, Nid2, Tagln, Wnt5b) or on day 14 after stroke (Col4a2, Col8a1, Cthrc1, Cxcl1, Gpc3, Tgfbr2)." (PMID 23251410, 2012). "A better understanding of the factors capable of reducing CXCL1 expression may prove beneficial in many neurological disorders, as higher levels of this chemokine can be detected in CSF from patients experiencing neuromyelitis optica and stroke." (PMID 37765263, 2023). "In stroke models, it is demonstrated that infiltrating T lymphocytes (e.g., Th17 and Th1 cells) might regulate cytokines (e.g., Infγ and Il-17), chemokines (Ccl2 and Cxcl1), or ROS to degrade tight junction in the BBB." (PMID 37443034, 2023). "Within 24 h of having a stroke, the expression level of CXCL1 in the cerebrospinal fluid of patients positively correlates with the ischemic area, indicating that CXCL1 may participate in the regulation of brain tissue damage (Losy, Zaremba & Skrobanski, 2005)." (PMID 31667013, 2019). "Therefore, the post-stroke plasma increases in IL-6 and CXCL1 found in obese mice here could be due to increased release from the adipose tissue." (PMID 28798136, 2017). "Post‐stroke BHB therapy resulted in a substantial decrease in the expression of proinflammatory chemokines (CCL3, CXCL1, CXCL9, CXCL10), complement (C5/5a), cytokines (IFN‐γ), and myeloid cell activators (G‐CSF) in the ischemic hemisphere." (PMID 38666466, 2024). "CXCL1 and MCP-1 concentrations were significantly elevated in cases of stroke compared to the controls." (PMID 37266378, 2023).
Stroke (continued). "Elevations of numerous pro-inflammatory cytokines, including CXCL1 and MCP-1, have been identified in the serum of human stroke patients." (PMID 37266378, 2023). "Elevation of CXCL1 and MCP-1 in CSF from dogs with stroke is consistent with data from other species." (PMID 37266378, 2023). "Mean concentrations of CXCL1 (stroke-436 pg/ml, control-267 pg/ml, p = 0.01) and MCP-1 (stroke-196 pg/ml, control-66 pg/ml, p ≤ 0.0001) were significantly elevated in dogs with stroke when compared with control dogs." (PMID 37266378, 2023). "Real-time quantitative PCR measurements suggested the prominent elevation of multiple pro-inflammatory cytokines and chemokines, including IL-1β, IL-6, TNF-α, CCL2, CXCL1, and CXCL10 after stroke." (PMID 35761277, 2022). "It involves the stroke-mediated decrease of miR-98 and let-7g*, which in turn, triggers expression of pro-inflammatory mediators, such as CCL2, CCL5, CXCL1, and IP-10." (PMID 32766248, 2020). "The increased CXCL-1 and CXCL-2 levels in the brain tissue after stroke lead to accelerated leukocytes and particularly granulocyte accumulation and aggravate ischaemic tissue damage." (PMID 30700305, 2019). "IL-17A, produced mainly by activated Th17 cells, can induce the secretion of a variety of stroke-related cytokines, such as IL-6, TNF-α, IL-1β, CXCL1 and CXCL8." (PMID 29262579, 2017). "Stroke resulted in upregulated expression of adhesion molecules (P‐selectin, E‐selectin, and ICAM‐1) and chemokines (CC‐chemokine ligand (CCL)‐2, CCL‐3, CCL‐4, CCL‐5, and chemokine C‐X‐C ligand 1 (CXCL‐1))." (PMID 37122157, 2023). "Impressively, TXL could inhibit the stroke‐enhanced expression of adhesion molecules (P‐selectin and ICAM‐1) and chemokines (CCL‐3, CCL‐4, CCL‐5, and CXCL1)." (PMID 37122157, 2023). "Impressively, TXL could inhibit the expression of stroke‐induced upregulated adhesion molecules (P‐selectin and ICAM‐1) and chemokines (CCL‐3, CCL‐4, CCL‐5, and CXCL1)." (PMID 37122157, 2023). "dBET1 markedly reduced inflammation and oxidative stress after stroke, indicated by multiple pro-inflammatory cytokines and chemokines including IL-1β, IL-6, TNF-α, CCL2, CXCL1 and CXCL10, and oxidative damage markers 4-hydroxynonenal (4-HNE) and gp91phox and antioxidative proteins SOD2 and GPx1." (PMID 35761277, 2022). "In line with Trizol whole-brain mRNA data, Cxcl1 and Cxcl2 levels were profoundly ﻿reduced in Il1−/− mice 24 h after stroke, whereas Ccl2 was not significantly downregulated in input material from Il1−/− mice." (PMID 35384588, 2022). "However, only let-7g* was effective in reducing the stroke-driven increases in CCL3 (p < 0.05) and CXCL1 (p < 0.005), while miR-98 attenuated the increase in IP-10 (p < 0.05) only." (PMID 32766248, 2020). "Serum levels of CXCL1, a potent neutrophil chemokine, were found to be significantly elevated in aged animals over young animals, regardless of sham or stroke status (p=0.05)." (PMID 31927534, 2020). "Next, we examined the mRNA expression of CXCL1 and CXCL2 in the lung after stroke." (PMID 31447768, 2019). "Although neutrophil numbers in the blood were not analysed here in response to stroke, it is possible that more neutrophils were mobilised from the bone marrow in response to early increase (4 h) in CXCL-1 expression in obese mice." (PMID 26239227, 2015). "The lack of neutrophil trafficking into the liver of obese mice in response to stroke is consistent with the absence of CXCL-1 expression in this organ of these mice." (PMID 26239227, 2015). "Interestingly, Cxcl1 expression was persistently reduced 72 h after stroke in Il1−/− mice, whereas Cxcl2 and Ccl2 already tended to normalize to WT levels." (PMID 35384588, 2022). "In the same vein, JAK3 inhibition with 10 mg/kg decernotinib did not affect stroke-induced upregulation of Ccl2, Cxcl10, and Cxcl1, chemokines important for immune cell trafficking, nor proinflammatory mediators IL-1β, IL-6, Tnfα, Ptgs2, and Mmp-9 that exacerbate stroke damage." (PMID 28790974, 2017).
Stroke (continued). "The increase in brain chemokine expression (CXCL-1 and CCL3) and greater circulating blood neutrophil numbers that were observed in obese mice in the present study are likely responsible for the enhanced neutrophil infiltration into the brain in response to stroke." (PMID 26239227, 2015). "The high Cxcl1 mRNA levels in young but not aged rats at day 3 post-stroke suggest that the recruitment of EPCs may be more efficient in young animals." (PMID 24672479, 2014). "In stroke patients, increased cerebrospinal fluid and/or circulating IL-1β, IL-6, IL-10, and CXCL-1 (CINC-1/IL-8), monocyte chemoattractant protein-1, and TNF-α concentrations have been reported, and IL-6 in particular identified as a predictor of stroke outcome." (PMID 21714902, 2011).